CD4 (CD4 molecule)
Diseases named in the same sentence as CD4 in open-access papers (continued):
Sharing a sentence is not in itself a finding about the gene and the disease.
infection (continued). "In the spleen, elevated frequencies of GATA3+ CD4+ T cells were detected at 6 and 8 weeks post infection (part C), and at all three time points in the mesenteric nodes (part D), with frequencies again increasing as the infection progressed." (PMID 30653492, 2019). "On the other hand, Tap1−/− mice succumb to infection faster than Cd8−/− mice, and CD4+ T cells and NK lymphocytes from Tap1−/− mice produce reduced amounts of IFN-γ, indicating that TAP deficiency affects both acute and chronic phases of Toxoplasma infection." (PMID 30891027, 2019). "Both of these studies show that in the absence of Vpr, Env-positive virions are trafficked to the lysosome for degradation, thereby reducing the efficiency of macrophage to CD4+ T cell virus spread at low multiplicity of infection." (PMID 31396206, 2019). "The trend of the mode of HIV transmission and the stage of infection were changed over time in the evaluated cohort, with more cases with a CD4 count over 200/mm3 at the time of diagnosis, and more cases among MSM starting from 2010." (PMID 31795444, 2019). "We here demonstrate, that similar to non-opsonized HIV-1, mature DCs (i.e., LPS-DCs and Chlam-DCs) retained HIV-C particles in an infectious form and efficiently transmitted the virus particles to target CD4+ T cells through trans infection." (PMID 31178863, 2019). "Here, we further evaluated BCGΔBCG1419c's potential as a vaccine candidate against infection in a model resembling reactivation of LTBI upon CD4 deprivation." (PMID 30949177, 2019). "In the current study, we observed modest CD4+ T depletion in blood of hu-HSC mice as early as 3 days after infection that progressed over time." (PMID 30873181, 2019). "For example, in SIV, where the memory CD4+ T are the targets of infection, we observed a decrease in pathogen growth with a decrease in host immunity." (PMID 31288706, 2019). "Infection with L. infantum in malnourished animals induced a still more accented decrease in the percentage of CD4+Ki67+ and CD8+Ki67+ T cells (p < 0.001)." (PMID 31355153, 2019). "Infection of Haemophilus influenzae (NTHi) results in IL-12 and IL-7 synergistically controlling granzyme B by upregulating the IL-12 receptor in lung CD4+ and CD8+ T cells, which are used for increasing antibacterial response." (PMID 31915416, 2019). "Long term follow-up of a group of RhIVCH505-infected A1Ifnar-/- mice showed that CD4+ T-cells exhibited near complete recovery by approximately 40 to 50 days after initial infection." (PMID 31644426, 2019). "These Nef actions occur early upon infection of permissive cells, and is related to the CD4 downregulation function (reviewed in Pereira and daSilva, 2016)." (PMID 31736889, 2019). "The combined role of MNPs as both immune sentinels and APCs makes them the perfect vehicle for HIV to achieve transport from the site of infection in the anogenital epithelium to its primary target cells (CD4 T cells) in the submucosa or lymph nodes." (PMID 31616434, 2019). "In HIV-infected patients, TB-specific CD4 T cells are depleted early after infection and show functional alterations with decreased polyfunctionality and proliferative capacity." (PMID 30624717, 2019). "To characterize the infected CD4+ T cells, we performed a CD4+ T cell subtype-specific staining of cells collected at different time points after FV-mWasabi infection and subjected mWasabi+ CD3+ CD4+ cells to a t-SNE analysis." (PMID 30782653, 2019). "Studies of mouse models of flaviviral infection, including WNV, DENV, and YFV 17D, have suggested that CD4+ T cells, particularly Th1 subsets, contribute to protection against infection." (PMID 30677097, 2019). "Of note, for qualification purposes of this assay under Good Clinical Laboratory Procedures (GCLP) guidelines, it was observed that the median level of CD4 downregulation was 56% (range 39–83%) and 69% (range 34–89%) at 48 and 72 h post-infection." (PMID 31134085, 2019).
infection (continued). "Some studies suggest that while phagocytosis of infected CD4 T cells is more efficient, other methods of infection can occur." (PMID 31431552, 2019). "The numbers of neutrophils, macrophages, and CD4 T cells in the vagina were significantly increased after infection with C. albicans." (PMID 31333606, 2019). "In contrast, CD4+CD25+ Tregs cells are involved in the early stages of infection by Brucella, reducing the capacity of response of CD4+ effector T cells." (PMID 31481953, 2019). "One possible reason was that HIV-infected women generally experienced a slower disease development compared with men, which was corroborated by the fact that women tended to have higher CD4+ lymphocyte counts compare with men with similar infection time." (PMID 30876476, 2019). "Further, exosomes isolated from LdCen−/− infected DCs contained significantly reduced levels of miR-21 compared to LdWT infection, that promoted proliferation of CD4+ T cells in vitro." (PMID 31608064, 2019). "The increase in viremia during the acute phase is also marked by a concomitant decline in the CD4+ T-cell population attributable to direct virus-mediated cytotoxicity or infection-induced cytotoxic T-cells (CTL)-mediated killing of virus infected cells." (PMID 31487807, 2019). "In contrast, both routes of infection induced populations of CD4+ T cells producing IFN-γ, IL-2, and TNF." (PMID 31356170, 2019). "We found that primary infection elicited oligoclonal expansions of TH1-like EBV-specific CD4+ T cells armed with cytotoxic proteins that responded immediately ex vivo to challenge with EBV-infected B cells." (PMID 31308093, 2019). "Following trickle infection, we show resistance developed concurrently with intestinal immune responses shifting from CD4+ Th1 cell dominated to a CD4+ Th2 cell dominated response." (PMID 31730667, 2019). "In these compartments, the virions preserve their infectious capacity and can be the source of infection of CD4+ T lymphocytes." (PMID 30787929, 2019). "The acute phase of infection is mediated principally by macrophages, dendritic cells, NK and CD4+ cells." (PMID 30891027, 2019). "Taken together, these results indicate that IVag infection with ZIKV promotes vigorous systemic CD4+ and CD8+ T cell responses." (PMID 30677097, 2019). "We then cultured activated CD4 T cell with an R5-tropic virus at multiplicity of infection (MOI) of 10−1 and 10−4." (PMID 31398241, 2019). "These cytokines mediate the development of an effective CD4+ Th1 response which is critical to control the infection." (PMID 31469834, 2019). "The concurrent infection tests showed that the deletion of Vpu enhanced HIV-1 replication 1.5-fold in Jurkat-Raji/CD4 cell cocultures, but decreased it more than twice when VLPs purified from Jurkat cells were used to infect Raji/CD4." (PMID 31027334, 2019). "With regard to HIV-related features, HIV+ and HCV+/HIV+ patients were comparable in terms of CD4 nadir and % of CD4 count at time of analysis, duration of infection and suppressive cART." (PMID 31555223, 2019). "While CD4 is a necessary binding receptor for most HIV strains, CD8 T cells can temporally express CD4 after T cell activation permits making both CD4 and CD8 HIV-specific CAR T cells susceptible to infection." (PMID 31611880, 2019). "The 293T/CD4/X4 cell coculture infection was initiated by cotransfecting cells with wt or mutant HIV-1 packaging vector, pUCHR-inLuc-mR reporter vector, and expression plasmid encoding for NL4-3-derived Env." (PMID 31027334, 2019). "CD4+ T cell-B cell interactions are essential for control of parasite replication and elimination of infection." (PMID 30915078, 2019). "Adaptive immune response followed an expected trend in which the CD4+T cell population increased early after infection, while the CD8+T cell population remained constant throughout disease progression and did not change in frequency with or without infection." (PMID 30998796, 2019).
infection (continued). "Treatment of rats with anti-CD4 antibody (−3, −1, and 4 days post infection) resulted in >95% depletion of blood CD4+ T cells at time of challenge compared to IgG2α controls." (PMID 30846697, 2019). "In infected mice at the intestinal stage of infection, levels of CD4+ T cells at 6 dpi were markedly increased, while CD8+ T cells at 6 dpi were decreased." (PMID 31855175, 2019). "Two aspects of the CD4 T cell response to infection are strikingly different from that of the B cell repertoire." (PMID 31134060, 2019). "CXCL9 and CXCL11 were negatively correlated with CD4+ T-cell count at 1-year-infection point (CXCL9, r = − 0.5692, p = 0.0007; CXCL11, r = − 0.3741, p = 0.0349)." (PMID 31836011, 2019). "CXCR3 and its ligands, the IFN-γ-inducible C-X-C chemokines CXCL9, CXCL10, and CXCL11, are important for migration of activated CD4+ Th1 cells to inflamed tissues and sites of infection." (PMID 30915078, 2019). "HIV-1-infected primary CD4+ T cells were cultured for three days post infection to allow time for syncytium formation." (PMID 31757023, 2019). "Focusing on the first week of infection, during which time the memory CD4 T cells control viral titers, our analysis revealed focal perivascular, marked interstitial, and peribronchial collections of lymphocytes." (PMID 30641955, 2019). "No activation of CD4 or CD8 T cell responses was observed when mice were immunized with UV-inactivated virus, indicating that active infection with live ZIKV is required for the generation of CD4 and CD8 T cell-mediated immunity." (PMID 31382545, 2019). "HIV latency can be established in vitro following direct infection of a resting CD4+ T cell (pre‐activation latency) or infection of an activated CD4+ T cell which then returns to a resting state (post‐activation latency)." (PMID 31855322, 2019). "In our study, we verified that SLE patients with CD4+T cell depletion were more prone to develop infections." (PMID 30994732, 2019). "Failure to control infections has been observed in mice (and humans) that lack CD4+ T-cells, after sustained CD4+ T-cell depletion, or due to MHC/HLA class II defects." (PMID 31781092, 2019). "In our studies, the frequency of CD3+, CD4+ T cells still increased as expected following infection, and various CD4+ T cell subsets were similar between control and macrophage-depleted groups." (PMID 31455692, 2019). "Treated animals that eventually became infected had a delay in infection and had decreased damage in the gut-associated lymphoid tissue (GALT) with maintained CD4+ T cell numbers." (PMID 31390725, 2019). "We found, as expected, that the WT male mice had significantly higher numbers of PMN cells and CD4+ T cells during the chronic phase of infection than the HVEM KO male mice." (PMID 30918059, 2019). "Collectively, these data show that the CD4+CD8+ T cells are the main IFNγ producers upon challenge infection of immunized pigs." (PMID 31620134, 2019). "While high numbers of HCMV-specific CD4 T cells displaying a cytolytic phenotype are observed after infection and MCMV CD4 T cell epitope vaccination have been shown to protect against WT infection." (PMID 31627457, 2019). "Second-phase transfer (also termed cis-infection) involves infection of the MNP via CD4 and CCR5 co-receptor CCR5 and de novo synthesis of the virus before transferring the virus to a T cell." (PMID 31616434, 2019). "We then knocked down MALAT1 expression in PHA-P-activated primary CD4+ T cells by infection with lentiviruses containing MALAT1 shRNA for 2 days, and then infected them with replication competent virus HIV-1/NL4-3 for additional 4 days." (PMID 30788509, 2019). "Treatment with the combination VRC01+ anti-α4β7 significantly delayed infection acquisition, preserved CD4 counts and modified other virological and immunological parameters." (PMID 31427605, 2019). "The same can be said for infection following CD4 and CCR5-dependent entry, which varies across DC subsets and is also influenced by maturation." (PMID 31156637, 2019).
infection (continued). "Our data indicate a significant predominance of γδ T cell‐derived IFN‐γ in the recovered DM group and a mixed CD4+ and γδ T cell response in the non‐DM group within 1 year post infection." (PMID 31032897, 2019). "To test this, we analyzed the CD4 T cell response in animals receiving celecoxib treatment during the first infection." (PMID 31396568, 2019). "By the same token, reducing the drug concentration up to 9 times allowed for cis infection of CD4+ T cells." (PMID 31304185, 2019). "We quantified resistance exercise‐induced changes in the activation state of CD4+ T lymphocytes via surface protein expression and using a medically relevant model of infection (HIV‐1)." (PMID 31552706, 2019). "Since baseline CD4+ cell count was one major factor influencing TM infection, we evaluated the effect of CTX use on TM infection in three subgroups of CD4+ cell count: <50, 50 to 99, and 100–199 cells/μL using Kaplan-Meier method." (PMID 31851879, 2019). "In agreement with the previous reports that RBC-bound HIV occurs predominantly via DARC, we found that rCCL-5 substantially prevented HIV (R5-tropic) trans-infection of CD4+ T cells." (PMID 31772057, 2019). "Another strength of our study is the characterization of a protective effect of cART use, and high CD4 counts (> 500), on the CVD risk of HIV-infected individuals who survive hospitalization for severe infection." (PMID 30975092, 2019). "The establishment of productive HIV-infection however, is highly influenced by the activation status of CD4+ T cells, their response profile (preferential infection of Th17), and their location at the genital tract." (PMID 30787929, 2019). "Similar to CD8+ T cell exhaustion in chronic infection, the virus-specific CD4+ T cell response has been altered profoundly as infection persists." (PMID 30828337, 2019). "The participant experienced rapid disease progression, characterized by viral loads maintained above 100,000 RNA copies/ml and a rapid CD4+ T cell count decline over 32 weeks of infection." (PMID 31921139, 2019). "Indeed, position 39 in CD4 has experienced positive selection during primate speciation, and this may be because mutations that replace the asparagine protect individuals against infection." (PMID 31181085, 2019). "Further, neutrophils and CD4+ T cells were the only cell type that increased significantly in the brains of Ifnar1−/− mice following infection." (PMID 31511023, 2019). "A week after the infection, the percentage of CD4+ T cells in the lumber lymph nodes changed because of the activation of the adaptive immune system by C. albicans in the vagina." (PMID 30621597, 2019). "Since we have observed that CD20 was upregulated upon HIV infection and Rituximab efficiently targeted CD20dim CD4+ T cells, we next asked if Rituximab had any impact on ex vivo infection cultures of unstimulated PBMCs." (PMID 31420544, 2019). "Here we show in vitro that antiretroviral drugs did not block the ability of DCs and B cells to trans-infect CD4+ T cells, although they were effective in blocking direct cis infection of CD4+ T cells." (PMID 31304185, 2019). "In CD4+ T cells, the transcription factor Oct1/Pou2f1 is a dispensable transcription factor for T cell development and response to primary infection, but promotes expression of target genes, including Il2 and Ifng, under conditions of antigen reencounter." (PMID 31266507, 2019). "Another interesting cell subset that we observed in the FV-mWasabi-infected mice throughout the course of infection albeit at low levels was CD4+ T cells." (PMID 30782653, 2019). "Overall, the fungus triggered the cell-mediated immunity in the local vaginal tissues and the draining lymph nodes, resulting in increased percentage of CD4+ T cells in the lumbar lymph nodes post-infection." (PMID 30621597, 2019).
infection (continued). "CM from EM as well as CX and ECX fibroblasts preloaded with TFV and TAF were capable of partially protecting activated CD4+ T cells from infection by HIV (30–50% protection)." (PMID 30755713, 2019). "Efficient infection of CD4+ T-cells requires cell-cell contacts, and virus propagation from cell-to-cell depends on specific interactions between cellular and viral proteins." (PMID 31708905, 2019). "To explore the potential function of Na+/K+-ATPase in generating HIV-TCM, we incubated Na+/K+-ATPase inhibitor digoxin with HIV-infected CD4+ T cells, and maintained digoxin treatment throughout the 30 days as the infection progressed to latency." (PMID 31142734, 2019). "Another advantage of the LCMV-cl13 system is that by inducing CD4 T cell depletion at the initiation of infection, LCMV-cl13 would establish a chronic viremia for the life of the mouse." (PMID 30691215, 2019). "Profiling of the local response by BAL cell analysis revealed the induction of substantial frequencies of PPD-specific cytokine+ CD4+ T-cells from 6 weeks post-infection onward, with on average strongest response signals at 12 weeks post-infection." (PMID 31736945, 2019). "Our results show that central memory (CM) CD4 T cells from SIV infected female macaques differentially regulate a significantly larger number of genes at day 4 post-infection (PI) as compared to males." (PMID 31490965, 2019). "HIV-1 acquisition requires a series of orchestrated events that lead to systemic infection, beginning with viral entry through the genital epithelium and followed by the productive infection of distinct CD4+ target cells that reside within the mucosa." (PMID 31114569, 2019). "We reasoned that this model would clearly differentiate histological changes that were driven by memory CD4 T cells recognizing and responding to antigen in the lung versus those that were driven by infection and infection-induced inflammation." (PMID 30641955, 2019). "CD4 T cells specific for HA are also critical in the protective antibody responses to infection and vaccination because of their role in the germinal center response, high affinity antibody production and B cell memory." (PMID 31694141, 2019). "We did not detect significant differences in subsequent viral load, viral set-point, or CD4 decline post-infection between groups infected during low-dose period." (PMID 31434895, 2019). "Viruses generated from these constructs expressed high levels of SBP-ΔLNGFR 48 hr post-infection, and depleted CD4 and tetherin to a similar extent." (PMID 30857592, 2019). "These initial expansions are rapidly culled to leave small populations of TCM and TEM CD4+ T cells that persist throughout the chronic phase of infection." (PMID 31308093, 2019). "Upon challenge infection, CD4+T cells constituted 7.4–12.6% of the total splenocytes, and a large proportion of the CD4+T cells exhibited a CD69+/CD11a+ phenotype (range: 7.7–22%) indicative of T cell recruitment and early activation." (PMID 31293599, 2019). "At day 10–13 post-infection, peptide epitopes recognized by the elicited CD4 T cells were identified by a sequential method involving a peptide pooling matrix, which we described in detail previously." (PMID 31694141, 2019). "In activated CD4+ T cells, the RT activity peaked on average at 10 days post infection in cells from either the control or experiment sessions, then declined due to virus‐induced cell death." (PMID 31552706, 2019). "During the last few years, several studies have shown that DCs have the ability to transfer HIV-1 particles to target CD4+ T cells and facilitate their infection, in a process known as trans-infection." (PMID 31244850, 2019). "This difference remains statistically significant (P = 0.009) in the multivariate analysis, adjusting by age, gender, total and nadir CD4 cells, transmission route and time of infection." (PMID 30944340, 2019).